IL6 (interleukin 6)
Diseases named in the same sentence as IL6 in open-access papers (continued):
Sharing a sentence is not in itself a finding about the gene and the disease.
Sepsis (continued). "Serum IL6 levels were greater in patients with severe sepsis at ICU admission (median 741.8 pg/mL, IQR 578–1247, n = 50) than patients with infection (median 80 pg/mL, IQR 61–105, n = 49, P < 0.0001)." (PMID 23935244, 2013). "The current study shows that the median serum level of IL-6 is higher in cases with sepsis in comparison with control healthy infants." (PMID 24570828, 2013). "To underline that TNF-α secretion was not an epiphenomenon with regard to monocyte apoptosis, we also investigated the reaction in response to the pro-inflammatory cytokine IL-6, the secretion of which is well documented in clinical sepsis." (PMID 23349721, 2013). "Early administration of high-dose BHT (CLP + BHT-H6) significantly reduced elevations of IL-6 and IL-10 as compared with the sepsis-control group at 12 hrs postoperatively (bP < 0.05, IL-6: 868.24 versus 3177.64 pg/mL; IL-10: 85.35 versus 229.45 pg/mL)." (PMID 23762108, 2013). "Hyporesponsiveness for LPS stimulation was seen in patients with severe sepsis compared to simple sepsis patients for IL6, IL8, IL10 and TNFα reaching significant results for TNFα." (PMID 23414215, 2013). "In at least one well-controlled study,34ethnicity played a major role in modifying associations between polymorphisms in immunologically relevant genes (IL-6 and CD14) and sepsis-related outcomes." (PMID 24310803, 2013). "A relationship between corticosteroid administration and sepsis was suggested when the administration of low-doses of hydrocortisone to septic patients significantly reduced circulating levels of IL-6 and of IL-8." (PMID 24350219, 2013). "LPS induces expression of pro-inflammatory cytokines, such as TNF-α and IL-6, which are involved in the pathogenesis of sepsis and are also an early predictors of organ dysfunction." (PMID 23564188, 2013). "The study design of this study is based on our previous report, in which the prognosis of septic rats was followed up for 3 days after CLP, and IL-6 and IL-10 were found to be good predictors of sepsis mortality." (PMID 23762108, 2013). "In contrast, systemic serum levels of pro-inflammatory cytokines of TNF-α and IL-6 were elevated during the first days after induction of sepsis and the creation of the wound verifying the septic state of the mice." (PMID 24086305, 2013). "To determine if circulating IL-6 appeared in the urine in sepsis-induced AKI for the same reasons, we performed a similar experiment." (PMID 24265742, 2013). "Multiple studies have shown that IL-6 is a biomarker for adverse outcomes in settings such as trauma/hemorrhage and sepsis and specifically of poor outcome in trauma." (PMID 24312451, 2013). "Circulating levels of IL-6 have been shown to be excellent predictors of the severity of ARDS of different aetiologies such as sepsis and acute pancreatitis." (PMID 24204926, 2013). "Consistent with previous studies, our data showed that the increased serum and tissue TNF-α and IL-6 levels in mice with early stages of sepsis were down-regulated by DXM." (PMID 24244697, 2013). "Previous studies have shown that elevated fetal IL-6 levels at birth are a risk factor for EONS and other neonatal morbidities as sepsis-induced disseminated intravascular coagulation, pneumonia and cerebral palsy." (PMID 23894452, 2013). "In our study, IL-6 was higher in patients with clinical evidences of sepsis and even higher in those with a positive blood culture." (PMID 22708043, 2012). "IL-6 is an early mediator and has a longer half-life period than TNFα and IL-1β and that intrinsic property makes it possible to use IL-6 as a marker of sepsis and SIRS." (PMID 24049646, 2012). "Patient with severe sepsis and those with sepsis on the ED with an acute abdomen can superiorly be differentiated by levels IL-6 and lactate." (PMID 22800189, 2012). "From these results, it is suggested that high IL-6 level is an independent marker of severity of sepsis." (PMID 22494810, 2012).
Sepsis (continued). "Other indicators of fetal sepsis and/or fetal inflammatory response syndrome were elevated IL-6 and S100A8 in placental tissues." (PMID 22952869, 2012). "With this background, we retrospectively investigated the correlation between blood IL-6 level and blood glucose level in patients with sepsis." (PMID 22494810, 2012). "During acute sepsis, the release of pro-inflammatory cytokines, such as IL-1β and IL-6, and the immune modulatory cytokine, IL-10, by innate immune cells such as macrophages, granulocytes and natural killer (NK) cells has been well documented." (PMID 22742734, 2012). "WMI was increased in infants with clinical early-onset sepsis and higher plasma levels of IL-8, IL-6, and TNF-α." (PMID 22530124, 2012). "Patients with positive blood culture sepsis had also higher values of IL-6 compared to the patients with clinical sepsis at the time of admission." (PMID 22708043, 2012). "These include both early- and late-onset sepsis, as well as NEC and are generally associated with high plasma levels of IL-6, IL-8, and TNF-α." (PMID 22530124, 2012). "The results demonstrate that impedance aggregometry using collagen as the activator was a better biomarker for the diagnosis of severe sepsis in critical illness than procalcitonin, interleukin 6 and C-reactive protein." (PMID 23088388, 2012). "They had a higher serum level of PCT and IL-6 on 12–24 hours after admission when compared to the patients with uncertain sepsis." (PMID 22708043, 2012). "IL-6 is one of the first acute phase cytokines released in sepsis/endotoxemia and is followed by increases in the levels of IL-1β, IL-8, TNF-α and IL-10." (PMID 23078757, 2012). "IL-6 is responsible for thrombosis during sepsis, while HGF potently inhibits IL-6 production in LPS-primed macrophages." (PMID 22536224, 2012). "Both IL-6 and IL-10 were significantly higher in patients with sepsis and both decreased markedly from enrollment to the end of the study." (PMID 22742734, 2012). "The role of IL-6 in murine sepsis has been somewhat controversial, since data from the literature are conflicting in relation to survival of IL-6 knockout mice subject to cecal ligation and puncture." (PMID 23137350, 2012). "Sequential measurements of ALT, AST, PCT and IL-6 during the early postoperative period can be used for early differentiation of sepsis and postoperative SIRS after oesophagectomy." (PMID 22742451, 2012). "On the other hand, elevated plasma concentrations of IL-6 predict AKI in patients with severe sepsis and mortality in sepsis correlates with the degree of IL-6 up regulation." (PMID 23173923, 2012). "In this present study, serum fT3 levels were found to be negatively correlated with IL-6 values at the 2nd week of the study, a time at which the sepsis rate was the highest." (PMID 22672862, 2012). "In another study, Mokart and colleagues investigated PCT and IL-6 to predict sepsis development in patients who had undergone gastrointestinal or gynaecological tumour resections." (PMID 22742451, 2012). "We have measured the blood level of IL-6 for real-time monitoring of the severity of hypercytokinemia, and previously reported the usefulness of blood IL-6 measurements in patients with sepsis." (PMID 22494810, 2012). "TNF, being an endogenous pyrogen, is able to induce fever, to induce apoptotic cell death, to induce sepsis (through IL1 & IL6 production), to induce cachexia, induce inflammation, and to inhibit tumorigenesis and viral replication." (PMID 22754316, 2012). "We have routinely measured blood levels of IL-6 in all patients with sepsis since 2000 to assess the severity of hypercytokinemia, and we have reported the clinical usefulness of the routine measurement of IL-6 levels in septic patients." (PMID 22494810, 2012).
Sepsis (continued). "Cardiomyocyte (CMs) isolated from wild mice undergoing sepsis produced high levels of IL-6, TNF-α, IL-1β, MIP-1α, MIP-2, MCP-1, and KC, while CMs from C5L2-deficient mice secreted significant low level of the inflammatory mediators." (PMID 23233853, 2012). "For example, a recent study demonstrated that elevated serum IL-6 level during CLP-induced sepsis was due to increased level of C5a." (PMID 23233853, 2012). "“Cardiosuppressive cytokines,” the definition of which is based on their ability to disrupt normal contractile function of normal CMs, have been described in patients with sepsis, and include IL-6, TNF-α, and IL-1β." (PMID 23233853, 2012). "Patients with clinical evidence of sepsis had a significantly higher serum level of IL-6 compared to the patients with uncertain sepsis at the time of admission (p< 0.05)." (PMID 22708043, 2012). "IL-6 plays an important role in innate and acquired immune responses and is up-regulated during sepsis." (PMID 23028840, 2012). "In normal healthy subjects free of inflammation, IL-6 concentrations are typically quite low, in the range of 0.2–7.8 pg/mL but can exceed concentrations of 1600 pg/mL in sepsis." (PMID 22347395, 2012). "After multivariate regression logistic analysis, when assessed as a pair, a high IL-6 concentration and a persistent mHLA-DR decreased expression were found to be in relation with the development of sepsis with the best predictive value." (PMID 22431998, 2012). "Our retrospective study including 153 patients with sepsis indicated that a high IL-6 level was correlated with hyperglycemia and difficulties in glucose control." (PMID 22494810, 2012). "Among the conventional biomarkers of sepsis, an interleukin 6 concentration showed significant differences between survivors and non-survivors, while procalcitonin and C-reactive protein failed." (PMID 23088388, 2012). "At the 2nd week, the period at which the frequency of sepsis and low T3 rate were the highest, serum T3 level was negatively correlated with IL-6 (r=-0.49, p=0.001) and CRP (r=-0.33, p=0.03) levels." (PMID 22672862, 2012). "Interleukin 6 was even lower in patients with severe sepsis (when compared with postoperative patients)." (PMID 23088388, 2012). "The main inflammatory mediators that contribute to myocardial depression in sepsis include interleukins (IL-2, IL-4, IL-6, IL-8, and IL-10), gamma interferon (IFN-γ), TNF-α, IL-1β, and C5a." (PMID 22482045, 2012). "IL-6 is more of a marker than a mediator of sepsis, and it is a good predictor of mortality in septic shock." (PMID 22482045, 2012). "Serum IL-6 levels, a major predictor of mortality in human and mouse models of sepsis, were elevated 8-fold in septic control mice but remained unaltered in septic Mttp-IKO mice." (PMID 23145105, 2012). "Interleukin-2 is a proinflammatory cytokine as interleukin-6, tumor necrosis factor-α, and interferon-γ, which participate in the inflammatory response regulation in sepsis." (PMID 22645477, 2012). "In our study, it was observed that the relation between IL-6 and T3 was more striking at the 2nd week of life, the time at which sepsis rate was also the highest." (PMID 22672862, 2012). "Depending on this view, exogenous administration of rmMFG-E8 attenuated inflammation by reducing pro-inflammatory cytokines, TNF-α, IL-6 and IL-1β in sepsis as well as other diseases where LPS-TLR4 signaling is predominant." (PMID 22114683, 2011). "To verify the prognostic potential of sFas in relation to the established prognostic marker IL-6 for sepsis development after major trauma, we established ROC curves for both parameters at each time point." (PMID 21232130, 2011). "Interleukin-6 (IL-6) is an important mediator of the acute phase reaction in response to inflammation in sepsis." (PMID 21687569, 2011). "In other words, despite high plasma protein levels of IL-6 in sepsis, the actual gene expression in circulating leucocytes is expected to be very low." (PMID 22044529, 2011).
Sepsis (continued). "The direct pulmonary insult (acid instillation) was associated with a greater increase in plasma IL-6 and TNF-α concentrations, but the indirect pulmonary insult (sepsis) resulted in increased plasma ICAM-1 concentrations." (PMID 22204611, 2011). "This single-centre prospective observational study showed that serum PCT levels are more valuable than serum CRP, LBP, and IL-6 levels in discriminating sepsis from SIRS in critically ill patients." (PMID 21687569, 2011). "At 24 h after induction of sepsis, the IL-6 levels in the sera of plg+/- mice were also significantly lower than those in WT mice, but significantly higher than those in plg-/- and tPA-/-/uPA-/- mice." (PMID 21931850, 2011). "The strong positive correlation between plasma KT ratio and IL6 concentration is consistent with findings in murine models of sepsis where IDO−/− mice or mice treated with IDO inhibitors have lower plasma IL6 concentrations." (PMID 21731667, 2011). "TNF-α and IL-6 have been considered to be the primary mediators of sepsis, and a positive correlation has been found between serum IL-6 and TNF-α levels and multiple organ failure." (PMID 21931850, 2011). "In sepsis, blockade of IL-6 improved the survival of WT mice to a level that is close to plg-/- mice." (PMID 21931850, 2011). "Above results support the concept that IL-6 level in the early stage of severe sepsis can be a good predictor of mortality." (PMID 21939530, 2011). "The functions of IL-6 in sepsis include induction of acute phage protein production and T- and B-cell differentiation and growth." (PMID 21939530, 2011). "IL-6 levels were comparable in WT mice and plg-/- mice at 6 h, for both the infection model and the sepsis model." (PMID 21931850, 2011). "For this reason, culture models of sepsis have been developed which utilize incubation of healthy cells with bacteria, endotoxin (LPS), or exogenous inflammatory mediators such as TNFα or IL-6." (PMID 20593014, 2010). "It has been found to be a very potent immunostimulating agent by priming macrophages to produce cytokines, like TNF-a and IL-6 in blood of healthy humans as well as in blood of immunosupressed patients with sepsis and after cardiopulmonary bypass." (PMID 20604971, 2010). "CRP, IL-6 blood level, and mortality were significantly higher in the septic shock group (n = 57) than in the sepsis group (n = 127) (P < 0.001)." (PMID 20202204, 2010). "When evaluating the severe sepsis and sepsis groups separately, Gas6 correlated to IL-6, bilirubin, INR, procalcitonin and number of failing organs." (PMID 20731857, 2010). "Plasma levels of IL-6 were significantly elevated at the onset of sepsis compared with the postoperative and the volunteer groups." (PMID 20847814, 2010). "Many studies were conducted to evaluate the value of circulating IL-6 concentrations as indicators of clinical outcome in patients with severe sepsis, correlating high levels with fatal outcomes." (PMID 20076757, 2010). "Established biomarkers for the diagnosis of sepsis are procalcitonin, interleukin 6, and C-reactive protein." (PMID 20929576, 2010). "Day 1 mean and median levels of D-dimer (ng/ml) and IL-6 (pg/ml) stratified by severe sepsis, PCT, and those who arrived to ED within 24 hours of symptom onset." (PMID 21085465, 2010). "The highest IL-6 serum/plasma concentrations are reached during sepsis, therefore it appears to be a good marker of the severity of infection." (PMID 20847814, 2010). "The lysis index proved to be a better biomarker for sepsis in critical illness than procalcitonin, interleukin 6, or C-reactive protein." (PMID 20929576, 2010). "On the other hand, due to strong correlation of IL-6 with scoring systems in all of measured days, level of IL-6 is also trustworthy for evaluation of severity of sepsis." (PMID 22615611, 2010). "The IL-6 blood level was significantly higher in the septic shock group than in the sepsis and in the severe sepsis groups." (PMID 20202204, 2010).
Sepsis (continued). "Recent studies have documented elevated levels of IL-1 beta, IL-6, IL-7, IL-8, IL-10, IL-13, and tumour necrosis factor-alpha in septic shock patients than in those with severe sepsis." (PMID 20490277, 2010). "In humans, IL-6 and IL-8 elevations correlated significantly to lactate levels (as a measure of tissue hypoxia) in sepsis." (PMID 20181046, 2010). "It is known that the persistence of TNF-α and IL-6 in the serum peak levels of cytokines reveals the onset of sepsis and predicts poor outcome in septic patients." (PMID 20230641, 2010). "NF-κB, a ubiquitous transcription factor, is responsible for the transcription of a diverse range of genes involved in sepsis and is a critical regulator of genes that encode TNF-α, IL-6, chemokines, and other inducible enzymes." (PMID 20939898, 2010). "We found that in vivo neutralization of endogenous MCP-1 during acute sepsis led to substantial decreases in the transcript levels for IL-1α, IL-1β, and IL-6, as well as MCP-1 itself, in the diaphragm." (PMID 20950459, 2010). "The mRNA expressions of IL-6 and IL-1β in lung tissue were determined due to the role of these markers in the pathogenesis of sepsis and ventilator-induced lung injury (VILI)." (PMID 20546573, 2010). "In both postoperative and sepsis patients, mean values for procalcitonin, interleukin 6, and C-reactive protein exceeded the reference interval by far." (PMID 20929576, 2010). "The thromboelastometry lysis index proved to be a more reliable biomarker of severe sepsis in critically ill adults than were procalcitonin, interleukin 6, and C-reactive protein." (PMID 20929576, 2010). "Clinical and experimental studies suggest that cytokines, especially TNFα, IL-1β and IL-6 appear to play a pivotal role in mediating the hemodynamic effects and the release of cardiac troponin in patients with severe sepsis and septic shock." (PMID 20140242, 2010). "Consistent with the intense host inflammatory response found in ARDS and sepsis, high titer autoantibodies were detected to a number of cytokines including IL-6, interferon-ω, interferon-γ and interleukin-1-α." (PMID 20946647, 2010). "Raised levels of Il6 have been described in a number of acute conditions such as burns, major surgery and sepsis." (PMID 20628605, 2010). "Among cytokines produced in the intestinal mucosa during sepsis and endotoxemia, interleukin (IL)-6 is particularly important because of its multiple significant biological effects." (PMID 20204057, 2009). "Release of both TNFα and IL-6 from monocytes was lower in patients with VAP-related sepsis than with sepsis related to other types of infection." (PMID 19883512, 2009). "While plasma IL-6 levels were able to predict outcome in a murine sepsis model, the data in humans is still controversial." (PMID 19781105, 2009). "Cytokine profiling for TNF-α and IL-6 level in elderly patients with sepsis helps in prognosticating the outcome." (PMID 19881187, 2009). "Early sepsis is characterised by hyper-inflammation and excess of pro-inflammatory mediators such as tumour necrosis factor-alpha and interleukin-1 and interleukin-6." (PMID 19552820, 2009). "Because IL-6 blockade with neutralizing Abs has been shown to be protective in CLP-induced sepsis, we next assessed the role of CB2 receptors in regulating IL-6 production during sepsis." (PMID 19641602, 2009). "Not surprisingly, different markers of systemic inflammation (eg, sICAM-1, sVCAM-1, IL-6) are significantly elevated during ongoing sepsis, whereas only IL-6 differed between patients after major abdominal surgery and healthy volunteers." (PMID 19538738, 2009). "• Pituitary mRNA expression of proinflammatory TNF and IL-6 is upregulated during experimental sepsis." (PMID 19196477, 2009). "Perhaps significantly, during trauma-hemorrhage and sepsis, two disease etiologies with significant parallels to human YF, liver-resident Küpffer macrophages are a major source of IL-6 and MCP-1." (PMID 19816561, 2009).